GSTM1 (glutathione S-transferase mu 1)
Diseases named in the same sentence as GSTM1 in open-access papers (continued):
Sharing a sentence is not in itself a finding about the gene and the disease.
meningioma (continued). "A biomarker of meningioma recurrence has the potential to shape personalized medicine approaches in the future by allowing clinicians to match the extent of initial meningioma treatment to the risk for later recurrence based on the presence or absence of a GSTM1 null genotype." (PMID 39726707, 2024). "Additionally, a gene-set enrichment analysis of GSTM1 null meningiomas versus GSTM1 expressing meningiomas identified cell-to-cell interaction and angiogenesis pathways upregulated as well as transmembrane transport and intracellular signaling pathways downregulated in GSTM1- meningiomas." (PMID 39726707, 2024). "Thus, loss of GSTM1’s ability to detoxify electrophiles generated by xenobiotic-induced reactive oxygen species, along with the lack of compensation by other GST genes, increases cancer susceptibility and prompts further malignization of tumors, including meningiomas." (PMID 39726707, 2024). "GSTM1 hemizygous non-recurrent meningiomas either had two GSTM2 alleles or were hemizygous for GSTM2, where loss of a GSTM1 copy was inherited (variant C) or lost due to somatic chr1p deletion (variant D)." (PMID 39726707, 2024). "Taken together, our results present evidence that GSTM1 expression was completely absent in all recurrent meningiomas due to the GSTM1 null genotype resulting from inherited gene deletion and/or somatic deletion of chr1p, where GSTM1 is mapped." (PMID 39726707, 2024). "All recurrent tumors demonstrated the absence of GSTM1 expression and seven of 12 primary meningiomas showed GSTM1 expression." (PMID 39726707, 2024). "None the less, GSTM1 under expression is found in recurrent meningiomas from independent datasets, externally validating GSTM1- as a biomarker for 1p-22q-NF2-meningioma recurrence." (PMID 39726707, 2024). "Next, we compared mRNA expression profiles of GSTM1- and GSTM1+ subgroups to characterize differences between meningiomas with and without our marker of recurrence." (PMID 39726707, 2024). "Our results demonstrate that 1p-22q-NF2- meningiomas without expression of GSTM1 comprise the recurrent 1p-22q-NF2- meningiomas compared to those that express GSTM1, thereby addressing the heterogeneity in this existing molecular classification scheme." (PMID 39726707, 2024). "One postulated explanation for the relationship between GSTM1 under expression and meningioma recurrence is that GSTM1 function is necessary to remove substances secreted by meningiomas that stimulate their growth and without this host factor present meningioma growth is relatively less controlled." (PMID 39726707, 2024). "Our results demonstrated that five out of twelve primary meningiomas had no expression of GSTM1, suggesting that these patients’ meningioma might reoccur in the future." (PMID 39726707, 2024). "The most significant DEG in GSTM1 null meningiomas was upregulation of MAP1LC3C, which is located on chr1q43, and is required for the formation of autophagosomal membranes for autophagy-related processes and cell homeostasis, but is not routinely deleted in meningiomas." (PMID 39726707, 2024).
osteoarthritis (2 papers, 2019 to 2025). A noninflammatory degenerative joint disease occurring chiefly in older persons, characterized by degeneration of the articular cartilage, hypertrophy of bone at the margins and changes in the synovial membrane. "In this study, we evaluated the effects of treatment with A-ITC and P-ITC on the protein levels of the antioxidant enzymes HO-1, NQO1, GSTM1, and GSTA1 in the hippocampus of animals with osteoarthritis pain." (PMID 31905764, 2019).
pterygium (2 papers, 2010). A wedge-shaped fibrovascular lesion arising from the bulbar conjunctiva and extending to the cornea. "The analysis of the presence of GSTM1 polymorphisms or the null type in pterygium showed that 60 (58.3%) were the present type and 43 (41.7%) were the null type." (PMID 20700368, 2010). "Relationship of BPDE-like DNA adduct levels and CYPA1 and GSTM1 polymorphisms in pterygium patients." (PMID 20700368, 2010). "In this study, we analyzed the PAHs metabolic enzymes, CYP1A1 and GSTM1, and their gene polymorphisms in pterygium and compared them with control groups." (PMID 20596254, 2010). "The multiple logistic regression analysis showed that the CYP1A1 genotype is related to the risk of pterygium after an adjustment with GSTM1 polymorphisms." (PMID 20596254, 2010). "CYP1A1 and GSTM1 polymorphisms in pterygium analyzed by PCR-RFLP and PCR." (PMID 20700368, 2010). "Therefore, BPDE-like DNA adducts and CYP1A1 and GSTM1 polymorphisms were detected in this study to provide more molecular evidence to understand the cause of BPDE-like DNA adduct formation in pterygium." (PMID 20700368, 2010). "The effects of gender, CYP1A1, and GSTM1 polymorphisms on DNA adduct levels in pterygium patients." (PMID 20700368, 2010). "In this study, we try to detect the BPDE-like DNA adducts, using immunohistochemistry in 103 pterygium specimens, and we compare them with CYP1A1 and GSTM1 polymorphisms to understand the relationship between environmental exposure and genetic polymorphism in pterygium." (PMID 20700368, 2010). "Multiple logistic regression analysis of CYP1A1 and GSTM1 genotypes and the risk of pterygium." (PMID 20596254, 2010). "Therefore, we hypothesize that that the genetic polymorphisms of CYP1A1 and GSTM1 increase the risk of pterygium." (PMID 20596254, 2010). "Therefore, we hypothesize that the genetic polymorphisms of CYP1A1 and GSTM1 increase the risk for pterygium." (PMID 20596254, 2010). "The relationship between BPDE-like DNA adduct levels and CYP1A1 and GSTM1 gene polymorphisms in pterygium is not clear." (PMID 20700368, 2010). "Genotype distribution of CYP1A1 and GSTM1 genes among pterygium patients and control group." (PMID 20596254, 2010). "Therefore, we suggest that the role of GSTM1 in pterygium formation is more important in antioxidant defense than in PAH metabolism." (PMID 20596254, 2010). "However, no clear patterns were observed between the pterygium and control groups for significant associations with GSTM1 polymorphisms." (PMID 20596254, 2010). "Therefore, genetic polymorphisms of CYP1A1 and GSTM1 may contribute to BPDE-like DNA adduct formation and pterygium progression." (PMID 20700368, 2010). "Therefore, the genetic polymorphisms of CYP1A1 and GSTM1 may contribute to BPDE-like DNA adduct formation and pterygium progression." (PMID 20596254, 2010).
steatosis (2 papers, 2012 to 2018). Increased lipid within the cytoplasm of cells. "Several studies reported that GSTM1, GSTM2, GSTM4 and GSTM5 mRNA levels are suppressed in patients with steatosis and NASH." (PMID 30080863, 2018). "In contrast to GSTM2, GSTM1, GSTA4, and GPX4 which are up-regulated in the steatosis patients, GSTT1 is found to be down-regulated." (PMID 22969728, 2012). "Furthermore, GSTM1 and GSTM2 that are found to be up-regulated in the fibroblasts of the two steatosis patients are known to be induced by oxidative stress." (PMID 22969728, 2012).
toxic epidermal necrolysis (2 papers, 2021 to 2025). Toxic epidermal necrolysis (TEN) is an acute and severe skin disease with clinical and histological features characterized by the destruction and detachment of the skin epithelium and mucous membranes. "A study carried out with HIV-positive individuals in Mozambique, treated with nevirapine, identified that the development of Stevens–Johnson syndrome and toxic epidermal necrolysis was associated with the GSTM1 null allele." (PMID 40867808, 2025). "Moreover, GSTM1 null genotype has been related to the most severe and rare form of cutaneous drug reactions, Steven-Johnson syndrome, and toxic epidermal necrolysis (SJS/TEN) in HIV-positive patients receiving nevirapine." (PMID 33672092, 2021).
vitiligo (2 papers, 2019 to 2020). Generalized well circumscribed patches of leukoderma that are generally distributed over symmetric body locations and is due to autoimmune destruction of melanocytes. "Moreover, KBL was found to modulate vitiligo via the regulation of activity of multiple series enzymes such as tyrosinase (TYR), oxidoreductase (GSTP1, CAT, MPO, and GSTM1), and controlling signal transducer (NFE2L2)." (PMID 31781265, 2019).
acute GvHD (1 paper, 2021). "Polymorphisms of GSTA1, GSTM1, and GSTP1 were reported as risk factors for SOS and acute GvHD, while GSTA1 and GSTM1 have been associated with combined TRTs." (PMID 34956984, 2021).
acute monocytic leukemia (1 paper, 2022). Acute monoblastic leukemia (AML-M5), is one of the most common subtypes of acute myeloid leukemia (AML) that is either comprised of more than 80% of monoblasts (AML-M5a) or 30-80% monoblasts with (pro)monocytic differentiation (AML-M5b). "The acute monocytic leukemia (THP1) cell model was selected for the production of the CRISPR–Cas9 GSTM1- and/or GSTT1 knockout model, as we have the most patients with a relapsed AML." (PMID 34499222, 2022).
acute promyelocytic leukemia (1 paper, 2020). An aggressive form of acute myeloid leukemia (AML), characterized by arrest of leukocyte differentiation at the promyelocyte stage, due to a specific chromosomal translocation t(15;17) in myeloid cells. "In addition, the GSTM1/GSTT1 null genotypes are related to increased susceptibility to acute promyelocytic leukemia." (PMID 33083304, 2020).
adenoma (1 paper, 2007). A neoplasm arising from the epithelium. "The ratio (Q2) was also associated with an increased risk of high-risk and low-risk adenomas in individuals with the GSTM1 common allele and the GSTP1 codon 105 variant allele (Val allele)." (PMID 18093316, 2007). "In addition we found weak evidence of a modifying effect by the GSTP1 and GSTM1 genotypes on the ratio of total meat to total fruit, berry and vegetable intake in adenomas." (PMID 18093316, 2007).
atrial septal defect (1 paper, 2018). Interauricular communication is a congenital malformation characterized by a communication between the atrial chambers of the heart. "GST genotypes were also investigated in smokers with findings that the combined null genotype for GSTM1 and GSTT1 enzymes produced an additive effect for atrial septal defects when combined with parental exposure to second-hand smoke." (PMID 30257432, 2018).
autoimmune disease (1 paper, 2022). A disorder resulting from loss of function or tissue destruction of an organ or multiple organs, arising from humoral or cellular immune responses of the individual to their own tissue constituents. "Among the members of GSTs, glutathione S-transferase theta 1 (GSTT1) and GSTM1 in particular have become recent targets of active investigation into their role in increased susceptibility to IBD, Behçet’s disease, or other autoimmune diseases such as primary sclerosing cholangitis." (PMID 35743732, 2022).
Autoimmunity (1 paper, 2010). The occurrence of an immune reaction against the organism's own cells or tissues. "Since GSTM1 has known antioxidant functions, these data suggest that oxidative stress may be important in the development of RA-specific autoimmunity in genetically susceptible individuals." (PMID 21087494, 2010).
biliary atresia (1 paper, 2025). A rare, biliary tract disease characterized by progressive obliterative cholangiopathy of the intra- and extrahepatic bile ducts, occurring in the embryonic/ perinatal period, leading to severe and persistent neonatal jaundice and acholic stool. "Study have found that patients with the variant of biliary atresia (BA) known as Kotb disease all possess the glutathione S transferase M1 (GSTM1) and exhibit a deficiency in glutathione S-transferase." (PMID 40017650, 2025).
cerebral infarction (1 paper, 2019). An ischemic condition of the brain, producing a persistent focal neurological deficit in the area of distribution of the cerebral arteries. "Analysis of gene-gene interactions showed that the GSTM1 null genotype increased the cerebral infarction risk in carriers of the CYP1A1 C allele (P=0.015; OR, 1.47; 95% CI, 1.08–2.00)." (PMID 31638212, 2019). "Therefore, cerebral infarction may be associated with vascular inflammation and oxidative stress; AhR downstream genes, such as CYP1A1, GSTT1 and GSTM1, may serve important roles in the pathogenesis." (PMID 31638212, 2019).
cervix (1 paper, 2019). "The GSTM1 null variant caused cervix lesions, especially among HPV infection cases and among the Chinese and Indian populations." (PMID 31593112, 2019).
childhood cancer (1 paper, 2022). "In addition, recent research indicated that the glutathione S-transferase [GST] μ1 (GSTM1) appears to be an important gene in predisposition to ACT in survivors of childhood cancer." (PMID 35993025, 2022).
chronic hepatitis (1 paper, 2021). An active inflammatory process affecting the liver for more than six months. "Here, the GSTM1/GSTT1 double-null genotype was more frequently detected in patients with HCC than those with chronic hepatitis (10% vs. 2.1%, respectively) but this difference was not statistically significant." (PMID 34451956, 2021).
clear cell renal cell carcinoma (1 paper, 2022). "Interestingly, there is a similar case showing a synergistic effect from the alleles of GSTM1-null, GSTT1-present, GSTA1/T (low activity), and GSTP1/G (low activity) on promoting risk for clear cell renal cell carcinoma." (PMID 35572141, 2022).
co-infection (1 paper, 2013). "HCV co-infection and alcohol use may be associated with increased oxidative stress even in the presence of the GSTM1 coding for the functional antioxidant enzyme." (PMID 24416632, 2013). "While both HIV/HCV co-infection and alcohol consumption increased hepatic apoptosis, having the GSTM1 null genotype increased oxidative stress particularly for alcohol consumption." (PMID 24416632, 2013). "HCV status and alcohol use affected the association of the GSTM1 genotype with oxidative stress, with both HCV co-infection and alcohol use increasing the levels of oxidative stress in this cohort." (PMID 24416632, 2013).
diabetic neuropathy (1 paper, 2015). A chronic, pathological complication associated with diabetes mellitus, where nerve damages are incurred due to diabetic microvascular injury involving small blood vessels that supply these nerves, resulting in peripheral and/or autonomic nerve dysfunction. "We investigated the relation between polymorphism in genes related to oxidative stress such as GSTM1, GSTT1, and GSTP1 and the presence of T2DM and diabetic neuropathy (DN)." (PMID 26435566, 2015).
Dyskinesia (1 paper, 2015). A movement disorder which consists of effects including diminished voluntary movements and the presence of involuntary movements. "Genetic variability of phase II metabolism by a glutathione S-transferase enzyme coded for by GSTM1 has been associated with dyskinesia experienced in risperidone-treated patients." (PMID 26937359, 2015).
esophageal SCC (1 paper, 2010). "Another study investigated the incidence of the null genotype (homozygous deletions resulting in absent enzyme activity) of glutathione-S-transferase M1 (GSTM1) in three Chinese minorities, Kazakh, Uygur, and Tajik that experience varying incidence of esophageal SCC in a high incidence area." (PMID 24281163, 2010).
familial Alzheimer disease (1 paper, 2022). A degenerative disease of the brain that causes gradual loss of memory, judgment, and the ability to function socially. "A recent study has reported that the expression level of GSTM1 in the hippocampus is associated with memory ability in 5xFAD mice, which harbors human mutations in the genes for amyloid precursor protein and presenilin one related to early-onset familial Alzheimer’s disease." (PMID 36685285, 2022).
fetal growth restriction (1 paper, 2023). A fetus that does not grow beyond the 10th percentile of conventionally accepted weight for gestational age. "It is reported that exposure to organochlorine pesticides for pregnant women with mutant variants of GSTT1 and GSTM1 significantly increases the risk of fetal growth restriction." (PMID 37368581, 2023).
frontotemporal dementia (1 paper, 2022). Frontotemporal dementia (FTD) comprises a group of neurodegenerative disorders, characterized by progressive changes in behavior, executive dysfunction and language impairment, as a result of degeneration of the medial prefrontal and frontoinsular cortices. "To test whether elevated GSTM1 was specific to ALSP, we examined GSTM1 expression in post-mortem frontal gyrus tissue of AD and frontotemporal dementia (FTD) patients." (PMID 35713703, 2022).
gallbladder cancer (1 paper, 2019). "Some studies have examined the associations between CYP1A1, GSTM1, and GSTT1 polymorphisms and gallbladder cancer risk, but the findings have been inconsistent." (PMID 31870105, 2019). "In this study, we speculated that agricultural chemical pollution in the environment may be a critical risk factor for gallbladder cancer and examined if genetic variants of CYP1A1, GSTM1, or GSTT1 were associated with gallbladder cancer risk." (PMID 31870105, 2019).
gastric atrophy (1 paper, 2017). "The GSTM1 null genotype tended to increase the risk for gastric atrophy/intestinal metaplasia, but this influence was surprisingly modified by alcohol consumption in our studied population." (PMID 28182092, 2017). "We also noticed an increased risk of gastric atrophy/intestinal metaplasia for GSTM1 null genotype (adjusted OR = 1.55, 95% CI: [0.96, 2.53]) with a tendency towards statistical significance p = 0.074." (PMID 28182092, 2017).
gastric diseases (1 paper, 2017). "Current observations sustain the possible role of GSTM1 polymorphism in gastric diseases in our population, as a recent meta-analysis also proved its role in carcinogenesis in Caucasian population modulated by H. pylori infection and smoking." (PMID 28182092, 2017).
Hepatic fibrosis (1 paper, 2025). The presence of excessive fibrous connective tissue in the liver. "Recent studies suggest that aflatoxin exposure may exacerbate disease progression in patients with GSTM1 detoxification defects, leading to accelerated hepatic fibrosis." (PMID 40438780, 2025).
Hepatitis (1 paper, 2013). Inflammation of the liver. "The homozygous deletion (null genotype) of the GSTM1 gene showed the lack of the GSTM1 activity and would increase risk of anti-TB drug-induced hepatitis." (PMID 23460870, 2013).
hepatitis C infection (1 paper, 2010). "An exposed individual (i.e. a person with the GSTm1 deletion) who acquires hepatitis C, alcohol and U2 before acquiring aflatoxin and U1, is a non-causal (type 1) case." (PMID 20678223, 2010).
Hyperbilirubinemia (1 paper, 2019). An increased amount of bilirubin in the blood. "It has been shown that neonate carriers of GSTM1-null genotype are at high risk to develop pathologic hyperbilirubinemia and may have higher bilirubin levels." (PMID 31681027, 2019).
hypertriglyceridemia (1 paper, 2014). A laboratory test result indicating elevated triglyceride concentration in the blood. "Although the presence of double deletion genotypes of the GSTM1 gene is associated with hypertriglyceridemia and low HDL-cholesterol levels in healthy humans, it has not been shown directly that the null alleles actually change cardiac or coronary vascular GST activity." (PMID 24423050, 2014).
infarction (1 paper, 2025). A localised pathological necrosis of tissue resulting from obstruction of the blood supply usually by a thrombus, an embolus, or vascular torsion. "Further studies revealed that GSTM1 overexpression significantly inhibited the generation of intracellular and mitochondrial reactive oxygen species (ROS) under pathological conditions, suggesting that GSTM1 exerts an antioxidative stress effect in post-infarction fibroblasts." (PMID 40448227, 2025).